IL6 (interleukin 6)
Diseases named in the same sentence as IL6 in open-access papers (continued):
Sharing a sentence is not in itself a finding about the gene and the disease.
glomerulonephritis (42 papers, 2012 to 2025). A renal disorder characterized by damage in the glomeruli. "Although IL-6 is critical for the spontaneous development of glomerular nephritis and autoantibody production in Tank−/− mice, IL-6 deficiency failed to improve the survival rate of Tank−/− mice nor the prevalence of DAH." (PMID 34819357, 2022). "Another study evaluated the relevance of cytokines and immune globulin with glomerulonephritis in IgAV children and observed IgA1 levels in serum galactose deficiency and IgA, IgG, IgM, IL-6, IL-8, and IL-10 complex levels in urine were predictors of glomerulonephritis in IgAV children." (PMID 35935867, 2022). "IL-6 may thus act as an autocrine growth factor in the mesangium and dysregulated IL-6 production in mesangial proliferation linked with glomerulonephritis." (PMID 25520922, 2014). "MCP-1, IL-6 and IL-10 plasma levels showed a significant increase in mice with LPS-induced glomerulonephritis compared to control mice." (PMID 37475889, 2023). "Hep-hASC administration resulted in significant disease activity improvement including proteinuria, serum Cr and IL-6 levels, anti-ds DNA IgG antibody, glomerulonephritis, and immune complex in mice." (PMID 35095868, 2021). "IL-6 cytokine family members have been found to be elevated in the renal tissue of patients with kidney diseases, including diabetic nephropathy, glomerulonephritis and obstructive nephropathy." (PMID 30871285, 2019). "Subsequent studies examining IL-6 excretion in urine found higher levels in the urine of patients with glomerulonephritis compared to urine from healthy individuals or patients with other types of kidney disease." (PMID 30871285, 2019). "In 1989, it was reported that transgenic mice expressing human IL-6 displayed the pathology of glomerulonephritis, including the profound cell proliferation of mesangial cells in the kidneys." (PMID 30871285, 2019). "Moreover, we recently showed that HPSE inhibition by heparanase-2 treatment resulted in attenuated glomerulonephritis accompanied with decreased cortical mRNA expression of IL-6." (PMID 37475889, 2023). "Similarly, MCP-1 can also stimulate vascular endothelial cells to produce IL-6 through this pathway, and promote the development of glomerulonephritis." (PMID 35725391, 2022). "Abnormal expression of IL-6 might play an important role in the activation of polyclonal B cells and the development of glomerulonephritis in MRL/lpr mice." (PMID 32686763, 2020). "In fact, IL-6 urine levels increased with the severity of glomerulonephritis." (PMID 30871285, 2019). "Targeting IL-6 signalling is being examined as a treatment for glomerulonephritis." (PMID 30871285, 2019). "Furthermore, in SLE animal models, exogenous administration of recombinant human IL-6 in NZB/W mice accelerated the development of glomerulonephritis and increased mortality." (PMID 28380214, 2017). "The involvement of IL-6 in disturbed B-cell tolerance observed in patients with PRKCD mutation is supported by their phenotypical similarities with mice transgenically expressing human IL-6, including glomerulonephritis and enlargement of lymphoid organs due to massive B-lymphocyte proliferation." (PMID 27541826, 2016). "Furthermore, IL-6 administration exacerbated glomerulonephritis, while IL-6 blockade by means of anti-IL-6R or anti-IL-6 Ab prevented the onset and progression of the disease." (PMID 22315615, 2012). "Immunohistochemistry analysis showed that TNF-α, IL-6 and IL-10 were mainly expressed by mesangial cells and infiltrating macrophages in the glomeruli, as well as in the tubulointerstitial area and endothelium during the course of tubulointerstitial and glomerular nephritis in ECM." (PMID 38787228, 2024). "Upon complement system is activated by immune complex, sublytic C5b-9 can stimulate IL-6 and TGF-β1 secretion in mesangial cells in a p300-C/EBPβ-dependent manner which was demonstrated in mesangioproliferative glomerulonephritis (MPG) model." (PMID 28484449, 2017).
glomerulonephritis (continued). "Furthermore, we found an up-regulation of the pro-inflammatory cytokine IL-6 on d5 of acute anti-thy1 glomerulonephritis, confirming recent experimental studies which demonstrated convincingly that IL-6 is a strong mediator of mesangial cell proliferation and matrix expansion in glomerulonephritis." (PMID 27243813, 2016). "In contrast to TNF-α, IL-6 mRNA expression levels were near-significantly decreased by addition of HPSE2 in experimental glomerulonephritis but not in DN." (PMID 37180718, 2023). "Urinary IL-6 levels were elevated in patients with glomerulonephritis; however, the results did not define the type of primary glomerulonephritis." (PMID 27148252, 2016). "Importantly, systemic concentrations of TNF-α and IL-6 correlate with SLE disease activity in humans and treatment with exogenous IL-6 exacerbates glomerulonephritis in NZBWF1 mice." (PMID 25978333, 2015). "Furthermore, 6-mo-old Tank−/−Ifnar2−/− mice developed glomerulonephritis with mesangial cell proliferation and expansion of the mesangial matrix, whereas the absence of IL-6 completely prevented the mice from glomerulonephritis as previously reported." (PMID 34819357, 2022). "Severity of disease including IgG autoantibodies and glomerulonephritis are reduced in the absence of IFN-γ, IL-6 and IL-12p35." (PMID 23557436, 2013). "Taken together, these experiments suggest that the overproduction of IL-6 in ABIN1[D485N] mice contributes to germinal centre formation, antibody production, and glomerulonephritis, but is not required for the liver pathology or lung inflammation seen in this model." (PMID 31694920, 2019). "Notably, increased leukocyte recruitment and increased expression of IL-6 and CCL2 in the absence of Sdc1 have been observed in other in vivo models of inflammation, including delayed-type hypersensitivity, glomerulonephritis, and autoimmune encephalomyelitis." (PMID 28350804, 2017).
hyperferritinemia (42 papers, 2010 to 2025). "Hyperferritinemia caused by excess interleukin-6 (IL-6) release and macrophage activation results in increased availability of free iron within cells." (PMID 34793455, 2021). "CSS and secondary hemophagocytic lymphohistiocytosis (sHLH) are both associated with cytopenia, hyperferritinemia, and elevated interleukin-6 (IL-6) due to a viral driven hyper-inflammation and amplification of the immune response." (PMID 34185801, 2021). "In hepatocytes, on the other hand, the presence of IL6 signaling in SUDV-infected cells was predicted to induce hyperferritinemia, the suppression of STAT3, C-reactive protein (CRP), fibrinogen expression and the downregulation of acute phase response." (PMID 41181097, 2025). "From a pathophysiologic standpoint, our patient’s striking hyperferritinemia and systemic inflammation reflect the central role of cytokine dysregulation, particularly IL-1β, IL-6, and IL-18, which drive the clinical phenotype and systemic inflammation." (PMID 41384165, 2025). "The hyperferritinemia observed in SARS-CoV-2 with a pronounced increase in IL-6 is considered as a reliable indicator of uncontrolled activation of macrophages and the manifestation of sHLH." (PMID 39452484, 2024). "Hyperferritinemia in inflammatory and infective disorders is believed to be cytokine-mediated that implicate interleukin (IL) 1β, IL-6, IL-18, interferon (IFN)-γ, tumor necrosis factor-α (TNF-α) and macrophage-colony stimulating factor." (PMID 36844235, 2023). "The authors point out, among other aspects, high levels of interleukin-6, and hyperferritinemia, as well as the C-Reactive Protein, and D-dimer as important biomarkers of cytokine storm syndrome." (PMID 37515295, 2023). "The hyperferritinemia patients showed higher median IL-6, D-dimer, and hsCRP (P < 0.001) and lowered FIB level (P = 0.036)." (PMID 34865201, 2022). "Like interleukin-6, hyperferritinemia has been repeatedly reported as a good biomarker of CRS following CAR T-cell therapy." (PMID 36143085, 2022). "The pathogenesis of hyperferritinemia is thought to be cytokine-mediated, with interleukin (IL)1a, IL1b, IL6, IL18, tumor necrosis factor-a, c-interferon, and macrophage-colony stimulating factor all implicated." (PMID 36425471, 2022). "MODS and extreme hyperferritinemia were noted on HD 3, and on HD 4, IL-6 was elevated (81 pg/mL) as was soluble IL-2 receptor (8,043 pg/mL), with a normal value for IL-2." (PMID 35360192, 2022). "On HD 67, both IL-2 and IL-6 were elevated (1,060 and 12,376 pg/mL, respectively; the last dose of tocilizumab was 12 days earlier) and the following day extreme hyperferritinemia (31,085 ng/mL) was noted a fourth time." (PMID 35360192, 2022). "Clinical features of this syndrome are a persistent fever, hyperferritinemia, cytopenia, and elevation of inflammatory markers such as C-reactive protein and IL6." (PMID 34364393, 2021). "IL-6 modulates both the intestinal absorption and the iron release from macrophages through hepcidin, thus leading to hypoferremia and hyperferritinemia, which diminish the number of erythroid precursors." (PMID 34257378, 2021). "In this patient, the constellation of laboratory findings—including extreme hyperferritinemia, elevated inflammatory cytokines (IL-6, IL-10, TNF-α, IFN-γ), and multi-organ involvement—supports the presence of a cytokine storm or secondary HLH phenotype triggered by influenza A infection." (PMID 41245251, 2025). "IL-6 was elevated for each patient during at least 1 episode of extreme hyperferritinemia." (PMID 35360192, 2022). "Elevated IL‐6 and hyperferritinemia were predictors of death in COVID‐19 patients in China." (PMID 32473600, 2020). "In addition, recent evidence from coronavirus disease 2019 (COVID-19), identified hyperferritinemia and IL-6 as predictors of poor prognosis, suggesting that the mortality of these patients is related to a hyper-inflammatory process." (PMID 32699419, 2020).
hyperferritinemia (continued). "Interestingly, this study identified hyperferritinemia and interleukin (IL)-6, as predictors of poor outcome, thus suggesting a hyper-inflammatory process as the major cause of death." (PMID 32574264, 2020). "Therefore, cut-off values of IL-6, IL-8, and IL-10 for hyperferritinemia were calculated from the receiver operating characteristic curve." (PMID 24800252, 2014). "Tocilizumab, an IL-6 inhibitor, has been effective in MAS, but its use remains controversial due to its limited impact on hyperferritinemia." (PMID 40385895, 2025). "Extreme hyperferritinemia was noted on HD 14 concurrently with the onset of MODS; hypercytokinemia (IL-6 was 2,369 pg/mL) was presumed secondary to HLH." (PMID 35360192, 2022). "In this immune response balance, IL-1, IL-6, IL-18, IFN-γ, TNF-α, and hyperferritinemia are proinflammatory factors pushing the system towards a cytokine storm, with IL-6 elevation being the most reported to correlate with higher mortality." (PMID 34940401, 2021). "The association of hyperferritinemia and complications in patients with SARS-CoV-2 is indistinguishable, but the contributing factors such as IL-6 directly affecting ferritin synthesis can be a possibility." (PMID 33628256, 2021). "Regulation by proinflammatory cytokines such as interleukin (IL)-1b, IL-6, IL-18, MCSF, and INF-α provides a link to the disease pathogenesis and may explain rapid resolution of hyperferritinemia after targeted treatment and inhibition of key cytokines." (PMID 22536541, 2012). "Recurrent extreme hyperferritinemia was noted 1 week prior to her death (and 99 days following the first ferritin peak) concurrent with the onset of MODS and an increased IL-6 (510.9 pg/mL; she was treated with tocilizumab on HD 176, and IL-6 on HD 178 was 1,423 pg/mL)." (PMID 35360192, 2022). "Indeed, in addition to significantly reducing the serum levels of IL-6 and C-reactive protein (CRP), ruxolitinib could influence the regulation of several inflammatory cytokines (including IL-2, IL-5, and IL-10), and consequently reduce hyperferritinemia." (PMID 33489899, 2020). "In any case, recurrent extreme hyperferritinemia—often with MODS—was noted in 4 adolescents with systemic inflammation and elevated IL-6 who did not survive their hospitalization." (PMID 35360192, 2022).
prostatitis (42 papers, 2004 to 2025). An infectious or non-infectious inflammatory process affecting the prostate gland. "Prednisolone downregulates key pro‐inflammatory cytokines such as TNF‐α, IL‐1β, and IL‐6, which are implicated in the pathogenesis of both UC and chronic prostatitis." (PMID 40909304, 2025). "Interestingly, p62 deficiency in stromal fibroblasts has been associated with overexpression of IL6 and promotion of prostate tumorigenesis, supporting a role for p62 in regulating inflammatory responses in the tumor stroma." (PMID 26849807, 2016). "IL-6, a key pro-inflammatory cytokine in prostatitis, also plays a role in regulating miR-21 expression." (PMID 40178629, 2025). "Our results reveal that PARP1 aggravated prostatitis, and promoted macrophage and neutrophil infiltration at inflammatory sites and upregulates the expression of inflammatory cytokines such as IL-6, CCL2, and TNF." (PMID 40032778, 2025). "The activation of these factors is induced by pro-inflammatory mediators, in particular IL-6, and is known to promote prostate carcinogenesis as well as the development and progression of BPH." (PMID 35715415, 2022). "IL-6, a biomarker of prostate inflammation, was reported to contribute to the transition to CRRC through accessory activation of androgen receptors." (PMID 35392496, 2022). "Schistosomiasis induced inflammatory cytokines such as macrophage inhibitory cytokine-1, IL-6 and tumour necrosis alpha have been identified as potential mediators between prostatic inflammation and prostate carcinogenesis." (PMID 34048465, 2021). "The specific level of IL-6 is further recognized to be related to a poor outcome for these prostate diseases." (PMID 33276425, 2020). "Conversely, levels of soluble gp130, predicted to inhibit IL-6 transsignaling, are also positively correlated with PCa progression, suggesting a complex role for IL-6 in prostate malignancy." (PMID 29441069, 2018). "IL-6 cytokine is also involved in prostatitis development, increasing the proliferation and inflammatory infiltrate." (PMID 28386549, 2017). "In order to verify, at the systemic level our findings from BPH and localized PCA tissues, we comparatively evaluated circulating titres of IL-6, IL-7 and IL-15 in pre-operative sera from patients with prostatic diseases." (PMID 21943235, 2011). "The increased expression of IL-6, a major pro-inflammatory factor in prostatitis, suggests that inflammation may contribute to UPR-mediated PCa cell proliferation." (PMID 40178629, 2025). "It should be pointed out that in addition to this model, there are other induction methods of chronic prostatitis, such as the method of intraprostatic injection of 3% λ-carrageenan, and usually, they have similar cytokine profiles, such as elevated IL-1 and IL-6." (PMID 35154561, 2022). "Interleukin‐6 (IL‐6), interleukin‐8 (IL‐8), tumor‐necrosis factor‐α (TNFα), and interleukin‐1β (IL1β) are among the main cytokines that correlate with leukocytospermia and chronic prostatitis or chronic pelvic pain syndrome (CP/CPPS)." (PMID 33794059, 2021). "IL6 was reported to modulate progression, differentiation, survival, and angiogenesis of PCa, moreover it was shown to mediate AR activation in benign and malignant prostate models." (PMID 34822550, 2021). "Chronic inflammation and IL-6 in particular, are involved in colon and prostate carcinogenesis." (PMID 26595830, 2016). "In vitro IL-6 induces malignant conversion of benign prostate epithelia, although the role of SCs in this process is unknown." (PMID 22472196, 2012). "Increasing reports have demonstrated that suppressing the production of pro-inflammatory cytokines, such as IL-1β, IL-6, and TNF-α, can reduce the effect of prostatitis." (PMID 39291282, 2024). "In general, tests for IL-1, IL-6, IL-8 and TNF-α expression levels can be an indicator to verify the success of prostatitis." (PMID 37228599, 2023).
prostatitis (continued). "C57BL/6 mice received 5 mg/kg body weight of 1-adrenergic or 2-adrenergic receptor agonists intraperitoneally for five days and developed chronic prostatitis, characterized by increased pro-inflammatory cytokines TNF, IL-6, and chemokines CCL2, CCL3." (PMID 37228599, 2023). "A number of other kinases, enzymes and transcription factors with recognized roles in prostate carcinogenesis and cancer progression were found to contribute to signalling through PI3K/AKT, PPAR, ERK5, IL-6 and HMGB1." (PMID 28098159, 2017). "In a prostatitis mouse model of chronic pelvic pain, increased levels of IL6 were observed in the thalamus and cortex but not in the hippocampus." (PMID 36879305, 2023). "Therefore, the measurement of cytokine expression, particularly IL-1, IL-6, IL-8 and TNF-α, provides a reliable indicator of the success of the prostatitis model." (PMID 37228599, 2023). "In patients with BPH, the expression of interleukin-2 receptor (IL-2R) and IL-6 was higher in patients with prostatitis than in those without prostatitis." (PMID 36902608, 2023). "Even though there was a minor increment in SOX2 expression in our IL-6-induced prostate tumorspheres, it was not significant." (PMID 37987305, 2023). "Complement C4, complement C3, CRP, and IL-6 are commonly used in clinic to evaluate inflammation, but no causal relationship between C3, CRP, IL-6, and prostatitis was found in this study." (PMID 36071874, 2022). "Mechanistically, PARP1 promote the NF-κB expression, which could regulate downstream inflammatory cytokines, including IL-6, IL-10, IL-12p70, CCL2, IFN-γ in M1 macrophages, leading to the accumulation of proinflammation factors and ultimately exacerbating prostatitis." (PMID 40032778, 2025). "Indeed, the IL-6/STAT axis represents a link between inflammation and prostate carcinogenesis, which is the signal transducer and activator of transcription 3 (STAT3), a key modulator in the expression of a wide range of oncogenic genes and a player in prostate cancer energy." (PMID 36982868, 2023). "Moreover, the dose-dependent, anti-inflammatory action of pollen extract in nonbacterial prostatitis in rats leading to decreased levels of interleukin-1b, interleukin-6 and a tumour necrosis factor, decreases glandular inflammation has been demonstrated." (PMID 28431537, 2017). "In addition to causing an increase in all of the indices of inflammation in the tissue, the ethanol-DNBS-induced prostatitis resulted in an elevation of the tissue proinflammatory cytokines IL-6, IL-1β, and KC but not TNF-α." (PMID 24459330, 2013). "Additionally, the expression of IL-6, IL-12p70, CCL2 and TNF in the Parp1−/− model group was markedly reduced and IL-10 increased significantly compared to that in the WT model group, suggesting that PARP1 enhanced the inflammatory factors secretion in prostatitis." (PMID 40032778, 2025).